CTLA4 (cytotoxic T-lymphocyte associated protein 4)
Diseases named in the same sentence as CTLA4 in open-access papers (continued):
Sharing a sentence is not in itself a finding about the gene and the disease.
tumor (continued). "Anti-A2AR combined with either anti-PD-L1 or anti-CTLA-4 therapy showed efficacious tumor inhibition and led to up to 90% of tumors being eliminated in MC38 tumor-bearing mice that did not respond fully to anti-PD-L1 or anti-CTLA-4 monoclonal antibodies alone." (PMID 37834375, 2023). "In this model of ipilimumab function, T cells specific for tumor neoantigens are present but due to the suppressive function of CTLA4 in secondary lymphoid organs fail to generate appropriate anti‐tumor responses." (PMID 37435963, 2023). "IFN-γ expression in tumor cells correlated to the presence of CTLA4+ lymphocytes in lymph nodes (Z = 2.2; p= 0.027)." (PMID 36979688, 2023). "Preclinical studies have shown that blocking PD-1 or CTLA-4 in mouse models of glioblastoma increased long-term tumor-free survival and altered the inhibitory tumor microenvironment." (PMID 38067356, 2023). "As described in the introduction, ICIs including anti-CTLA-4, anti-PD-1 and anti-PD-L1 antibodies have been developed to restore the anti-tumor immune response." (PMID 38275827, 2023). "Expanding on this, AU-011 was combined with checkpoint blockade antibodies anti-CTLA-4 and anti-PL-L1, inducing complete or near-complete responses, respectively, in TC-1 tumor-bearing mice." (PMID 36839652, 2023). "Following CTLA-4 knockout, anti-tumor cytotoxicity and cytokine secretion by CTLs are notably increased, as well as the apoptosis and caspase activities of tumor cells." (PMID 37064017, 2023). "PD-L1, one of the PD-1 ligands, is widely overexpressed on tumor cells and infiltrating leukocytes, in contrast to the ligand of CTLA-4." (PMID 36677919, 2023). "Checkpoint inhibitors targeting receptors expressed on tumor-infiltrating T cells, such as PD-1 and CTLA-4, have revolutionized immuno-oncology, resulting in durable clinical remissions in a subset of patients across multiple cancer indications." (PMID 37819238, 2023). "Inhibitory immune checkpoints, such as PD-L1, PD-L2 and CTLA-4, are highly expressed in many tumors, and they impair the function of cytotoxic T cells in the tumor." (PMID 36765560, 2023). "Through this analysis, the combination of anti-mouse CTLA4 antibody with PRV-LAV was able to increase the therapeutic response against the injected tumor." (PMID 37891570, 2023). "While PD-1/CTLA-4 blocking prevents tumor growth in immunogenic tumors, triple therapy with DPP4i shrinks tumor size significantly more by recruiting eosinophils, which further solidifies the idea of T cell-eosinophil combination therapy." (PMID 37587450, 2023). "Anti-VISTA has shown immune stimulatory and tumor control promise when used alone, and in combination with anti-PD-1 and anti-CTLA4." (PMID 37762046, 2023). "A reduction in tumour development obtained by blocking CTLA-4 or PD-1 pathways, provides justification for the inhibition of immune checkpoints in cancer treatment." (PMID 36813833, 2023). "Despite the encouraging therapeutic effects of immune checkpoint inhibitors against PD-1, PD-L1, and CTLA-4 across multiple tumor types, the prognosis of metastatic PCa remains unsatisfactory mainly because of drug resistance." (PMID 37494663, 2023). "These preliminary findings in the tumor samples contradict the use of CTLA4 and PD-1 blockers as therapeutics." (PMID 36983005, 2023). "This facilitates tumor escape from T-cell immunity, thereby conferring resistance to anti-CTLA4 therapy." (PMID 37637050, 2023). "When T cells are activated, CTLA-4 expression is upregulated and the degree of T cell inflammatory response is reduced, thereby enhancing tumor immune escape in hepatocellular carcinoma." (PMID 37305582, 2023). "According to the Tumor Immune Dysfunction and Exclusion (TIDE) tool, the results exhibited that the Exclusion score, CAF score, PD-1, CTLA4, IDO1, and TIGIT score of the high-risk group were higher than those of the low-risk group." (PMID 37880682, 2023).
tumor (continued). "Immune checkpoint molecules, e.g., PD-1, CTLA-4, B7-H3, B7-H4, drive the paralysis of protective T cells in tumor beds." (PMID 37240071, 2023). "CTLA-4 inhibitors constitute another class of checkpoint inhibitors that amplify anti-tumor immunity via CTLA-4 inhibition on T cells, with ipilimumab being a well-characterized example." (PMID 38201238, 2023). "The adenovirus vector expressing anti-CTLA-4 mAb led to a significant delay in tumor growth, although this was only observed in combination with systemic Treg depletion." (PMID 37190279, 2023). "We investigated the effects of irradiated tumor burden and treatment sequences under the radiation and CTLA-4 blockade combination regimen." (PMID 37174706, 2023). "Based on this score, tumor samples were evaluated to determine if they would exhibit a favorable immune response to either PD-1/PD-L1 or CTLA4 inhibitors, or both." (PMID 37265698, 2023). "At the first stage of the study, the monitoring of the tumor growth in mice from the control and anti-CTLA-4-therapy groups was conducted up to the day of the lymph node sampling for FLIM and flow cytometry." (PMID 38435479, 2023). "CD39 inhibition, combined with TIM3 and PD-1 (alone or with CTLA-4 inhibition), improved tumor control, suggesting that scRNA-seq can predict new targets for combinational immunotherapies." (PMID 37176128, 2023). "Drugs that target CTLA-4, PD-1, and PD-L1 can modulate the body’s immune response to exert anti-tumor effects." (PMID 37305582, 2023). "The investigation of the current literature on immune checkpoint inhibition found that preclinical data show a decrease in tumor volumes and size when PD-1/PD-L1 is blocked, and similar results were observed with CTLA-4 blockade." (PMID 38201559, 2023). "The authors suggested that the GCs treatment should be initiated precisely after the start of immunotherapy, as soon as the tumor volume begins to decrease under the effect of CTLA-4 inhibitors alone." (PMID 36983597, 2023). "In recent years, much focus has been on developing immune checkpoint inhibitors (ICIs), monoclonal antibodies that target negative regulators of T cell activation, namely CTLA-4 and PD-1 on Treg cells or T cells and PD-L1 on tumor cells 173-176." (PMID 37064866, 2023). "Antibodies that target cytotoxic T-lymphocyte-associated antigen 4 (CTLA-4) such as ipilumumab and tremelimumab have been developed to enhance T-cell function and induce tumor regression." (PMID 36980308, 2023). "We correlated the tumor cell-intrinsic CTLA-4 protein expression quantified using the H scoring system with methylation levels in our UKB Non-ICB cohort." (PMID 37415208, 2023). "Meanwhile, TGF-β converts naïve CD4+ T cells into Treg cells, limits effector T cell proliferation and function, and augments FoxP3 and CTLA-4 expression, hence facilitating tumor growth and metastasis." (PMID 37868967, 2023). "Specifically, tumors irradiated with three fractionated doses (8 Gy each) showed synergy with anti-CTLA4 antibodies against both the irradiated tumor and a secondary untreated tumor." (PMID 37111624, 2023). "As expected, subsequent combination therapy with HPV mRNA-LNP vaccination and immune checkpoint blockade (anti-LAG3/anti-CTLA4) further promoted tumor regression." (PMID 37773254, 2023). "In contrast, tumor pHe neutralization improves the response to anti-CTLA-4 and anti-PD-1 mAb immunotherapies." (PMID 38102680, 2023). "Although the expression of CTLA-4 promotes tumor escape, inhibiting the antitumor response, it has been observed that expression is higher in peripheral blood cells and bone marrow and lower in lymph nodes, contrasting with the results found herein." (PMID 37370399, 2023). "Treatment of tumor-bearing mice with anti-PD-L1 alone or combined anti-PD-L1 and anti-CTLA-4 leads to the emergence of a population of PD-1+A2AR- CD8+ T cells that correlate with therapeutic outcome." (PMID 37914685, 2023).
tumor (continued). "In addition, the clinical efficacy of the monoclonal antibody ipilimumab (anti‐CTLA‐4) in patients with clinical melanoma is associated with selective depletion of Treg cells based on the FcγR‐dependent mechanism and an increase in the tumor‐infiltrating CD8+ T/Treg cell and Teff/Treg ratios." (PMID 37829505, 2023). "Focal radiation therapy is synergistic with CTLA4 inhibition leading to CD8+ T cell-mediated control of the irradiated tumor and its metastases and to occasional cures." (PMID 37620372, 2023). "Modified TheraVac consisting of N1+FSL-1+anti-CTLA4 (termed TheraVacM) in which R848 was replaced by FSL-1 yielded improved tumor control against 4T1 tumors." (PMID 37190294, 2023). "ICIs work by blocking lymphocyte receptors (such as PD-1 or CTLA-4), namely the ligand on the tumor cell (PDL-1), thus reactivating the physiological anti-tumor response." (PMID 38255667, 2023). "They intraperitoneally injected anti-CTLA-4 or anti-CD28, respectively, and found that, compared with the anti-CD28-treated or untreated control mice, anti-CTLA-4 treated mice showed inhibited B7-51BLimlO tumor growth." (PMID 36604694, 2023). "The blockade rate of CTLA-4 is very sensitive when it was above a threshold and there exists a critical blockade rate of CTLA-4 for tumor eradication." (PMID 36766849, 2023). "CTLA-4 competes with B7 for binding to generate negative regulatory signals, inhibiting full T cell activation and leading to tumor immune escape." (PMID 36604694, 2023). "The initial goal behind mABs targeting this molecule was to block inhibitory signals in activated effector T cells upregulating CTLA-4 and thereby unleashing their anti-tumor responses." (PMID 37359522, 2023). "It has been demonstrated that CTLA-4 blocker enhances anti-tumour response mainly by selectively reducing Tregs, with T cell activation being a secondary role." (PMID 38259489, 2023). "Ipilimumab is a CTLA-4 targeting humanized IgG1 monoclonal antibody, which demonstrates significant anti-tumor activity against a variety of cancers." (PMID 37415164, 2023). "Recent clinical trials have demonstrated the significant efficacy of pembrolizumab (PD-1 inhibitor) and ipilimumab (CTLA4 inhibitor) in anti-tumour activity, bringing in a new dawn in CCA treatment." (PMID 37142983, 2023). "Important predictors of ICI responses identified to date include high levels of microsatellite instability, TMB, and the expression of CTLA-4 and PD-L1 by tumor cells." (PMID 37095314, 2023). "We found that our poly(I:C) hydrogel significantly increased the anti-tumor response of either anti-PD-1 or anti-CTLA-4 therapy." (PMID 37467718, 2023). "CTLA4 inhibits T-cell activation to some extent, thus, anti-CTLA4 antibody immunotherapy can enhance the anti-tumor immune effects of T cells." (PMID 36759775, 2023). "The increase in the NADH α1 free form contribution and a corresponding decrease in the contribution of the NADH α2 protein-bound form correlate with a positive response to anti-CTLA-4 therapy expressed in the tumor growth inhibition." (PMID 38435479, 2023). "In patients with metastatic NSCLC, for example, radiotherapy was found to induce an enhanced blocking effect of anti-CTLA-4 antibody and induce an anti-tumor T cell response throughout the body." (PMID 37415744, 2023). "A previous study illuminated that ICI can target and block PD‐1 or CTLA4 to restore tumor‐specific T‐cell immunity." (PMID 36397666, 2023). "We observed that 2153L tumors were completely resistant to CTLA-4 and PD-1 blockade, but the combination with zotatifin sensitized this immune-cold tumor model to ICBs and enhanced survival compared with monotherapy." (PMID 37874652, 2023). "Considering the vital role of immune checkpoint molecules (PD-1, PD-L1, and CTLA-4) in the tumor immune microenvironment, we analyzed the expression of PD-1, PD-L1, and CTLA-4 in the two groups." (PMID 37428395, 2023).
tumor (continued). "The relationship between PIMREG and immune checkpoints, including PD1 (PDCD1), PD1-L1 (CD274), and CTLA-4, which play a crucial role in tumor immune evasion, was assessed." (PMID 37483962, 2023). "Immune checkpoint molecules, such as CTLA-4 and PD-1, disrupt antitumor immunity by attenuating T-cell activation in the event of malignancy, leading to a highly immunosuppressive tumor microenvironment." (PMID 37894750, 2023). "CTLA-4 has been shown to be more highly expressed in tumor cells and correlates with poor prognosis." (PMID 36982701, 2023). "Checkpoint inhibitors, such as PD-1/L1 and CTLA-4, have been successful at improving tumor control in selective cancers." (PMID 37046612, 2023). "Currently, dual immune checkpoint inhibitors with anti-PD-1/PD-L1 and anti-CTLA4 monoclonal antibodies are being widely evaluated for tumor therapy." (PMID 36817422, 2023). "PDL1 as well as CTLA4 blocking Ab significant slowed tumor growth of Adam2 O/E tumors, while control tumors showed little or no reduction in growth." (PMID 37258521, 2023). "TCGA‐KIRC cohorts were used to investigate CTLA4 expression in adjacent non‐tumor tissues and ccRCC tissues." (PMID 36397666, 2023). "The upregulation of PD-L1 or CTLA-4 expression can mediate the escape of tumor cells from the host immune response, lead to an immunosuppressive state, and inhibit the antitumor immune response in some tumor microenvironments." (PMID 37251440, 2023). "We investigated changes in the expression of CD80, CTLA-4 and PD-L1 molecules on tumour cells to understand their response to ICB + PDT." (PMID 37468749, 2023). "Some studies have shown that the combination of inhibitory receptors, such as the use of anti PD-1/PD-L1 and anti CTLA-4 antibodies, can significantly reverse the exhaustion of T cells and enhance the immune response of various tumor patients." (PMID 37550396, 2023). "Based on the results, we found that plant-produced anti-CTLA-4 2C8 elicited significant antitumor efficacy in syngeneic CT26-hPD-L1 tumor model." (PMID 37711295, 2023). "The increased efficacy of anti-CTLA-4 immunotherapy and enhanced overall survival in tumor models of syngeneic mice." (PMID 37069494, 2023). "When mHAdLyp.sT was combined with both anti-PD-1 and anti-CTLA-4 antibodies, primary 4T1 tumor growth was also significantly inhibited." (PMID 37790556, 2023). "It has been observed in multiple cancer types that upregulated PD-L1 on tumor cells can be a dominant resistance mechanism to RT and CTLA4, demonstrating persistent T cell exhaustion and rapid progression." (PMID 37221584, 2023). "The in vivo and in vitro CTLA-4 blockade decreased the activity of UV-induced Tregs, thus suggesting that the inhibition of this pathway is protective against tumor growth in the TIME." (PMID 37444461, 2023). "Immune checkpoint inhibitors, encompassing PD-1, PD-L1, and CTLA-4, have been identified as impeding anti-tumor immune responses in solid tumors." (PMID 37600802, 2023). "Treg cell depletion has shown promising results in preclinical cancer models, and anti-CTLA-4 therapy not only increases tumor-specific effector CD4+ T cells but also depletes intratumoral CTLA-4+ Tregs." (PMID 37346034, 2023). "Another well-known cancer immune checkpoint, CTLA-4 also regulates anti-tumor immune responses to promote protective immunity and maintain tolerance, along with LAG-3." (PMID 37509517, 2023). "In cancer, a sort of chronic inflammation with the presentation of tumor antigens persists, and multiple inhibitory receptors, such as CTLA-4, PD-1, PD-L1, LAG-3 and Tim-3, are permanently expressed, especially in MSI-H CRCs with a high immunoscore." (PMID 37511431, 2023). "TIM-3+Foxp3+ Treg cells express IL-10 and upregulate CTLA-4 and PD-1 expression, and these cells display more tumor suppressive function than TIM-3–Foxp3+ Treg cells." (PMID 36810098, 2023). "CTLA-4 immunohistochemistry was performed on the TMA of paired tumor and adjacent normal specimens (n = 20)." (PMID 37107632, 2023).
tumor (continued). "When combined with anti-CTLA-4 antibody, tumor growth was suppressed, and the survival time of mice was significantly prolonged." (PMID 37860188, 2023). "The mechanism of ICIs is restoring anti-tumor immunity by blocking immune checkpoints, such as cytotoxic T-lymphocyte antigen 4 (CTLA-4), programmed cell death protein 1 (PD-1), and programmed cell death protein ligand 1 (PD-L1)." (PMID 37020242, 2023). "High expression of PD-1 and/or CTLA-4 can downregulate T-cell activity, thereby reducing the efficacy of immunotherapy and facilitating the immune evasion of tumor cells." (PMID 37955668, 2023). "In this article, we have reviewed the extant literature elucidating the mechanisms underlying the response and resistance to ICB, with a particular emphasis on PD-1 and CTLA-4 pathway blockade in the context of anti-tumor immunity." (PMID 37614504, 2023). "The combination of ganetespib with anti-PD-1 (clone: 29 F.1A12, 135,204) and ganetespib with anti-CTLA4 (9H10) improved T-cell anti-tumor response and survival." (PMID 37460927, 2023). "Utilizing the TCGA cohorts, significant association (p<0.05) was observed between MNAI and PD1, PD-L1, CTLA-4, and immune cell infiltrations found in a majority of tumor types, which can explain its predictive powers towards certain immunotherapies." (PMID 37456231, 2023). "Consistently, we observed significantly higher expression of PD‐L1 and CTLA4 in malignant NK cells and stronger exhaustion of tumor‐infiltrating T cells in the EBVhigh samples." (PMID 37949673, 2023). "Inhibitors of CTLA-4 and PD-1/PD-L1can restore anti-tumor immune responses, resulting in long-term benefits in a substantial proportion of patients treated." (PMID 37063927, 2023). "Immune checkpoint inhibitors—inhibit tumor‐induced immunosuppression by blocking the interaction between PD‐1/PD‐L1, or CTLA‐4/B7 pathways to restore T‐cell antitumor immune response." (PMID 37039257, 2023). "It shows that the CTLA-4 blocking rate is very sensitive when it is above a threshold and there exists a critical CTLA-4 blocking rate for tumor eradication." (PMID 36766849, 2023). "CTLA-4 inhibitors block this interaction, leading to the activation of the anti-tumor immune response." (PMID 37175653, 2023). "Currently, the only method to determine the CTLA4 mRNA expression in the tumor is by invasive biopsy or surgical resection." (PMID 36397666, 2023). "Of note, 87.5% of the mice treated with the anti-CTLA-4 combination and 75% of the mice treated with the anti-PD-L1 combination exhibited complete tumor rejection and achieved tumor-free survival." (PMID 36650153, 2023). "Antibodies targeting PD1 and CTLA-4 have been developed with the aim of restoring T-cell functions and eventually halting tumor proliferation." (PMID 38068428, 2023). "The ligand–receptor interactions that lead to the activation of numerous immunological checkpoints also involve the cytotoxic T lymphocyte-associated protein-4 (CTLA4), PDL2 receptors expressed on immune and tumour cells, and others." (PMID 37238995, 2023). "Remodels the TME to trigger immune escape by upregulation of PD-1, PD-L1, CTLA-4, and multiple tumor-promoting inflammatory cytokines." (PMID 37138880, 2023). "Combining anti-CAIX and anti-CTLA-4 resulted in tumor recurrence about 2 weeks after treatment suspension, even after seemingly eradicating the tumor during the therapy window." (PMID 37373220, 2023). "Since CTLA-4 is mainly expressed in tumor-draining lymph nodes, established tissue-based biomarkers for predicting its inhibitory capacity are lacking." (PMID 38067301, 2023). "Specifically, preclinical trials have verified that the co-treatment of block PD-1 with CTLA-4, which negatively regulate the activation of T cells, can strengthen anti-tumor immune responses compared to a single drug therapy." (PMID 37194085, 2023).